TNF (tumor necrosis factor)
Diseases named in the same sentence as TNF in open-access papers (continued):
Sharing a sentence is not in itself a finding about the gene and the disease.
influenza (continued). "TNF has been extensively characterized as an important mediator in several inflammatory disorders, but until now, its CD8 T cell intrinsic role during influenza infection has been unclear." (PMID 23874808, 2013). "WT and TNFR2-/- OT-I cells recovered from influenza-infected mice were restimulated with OVA peptide and stained for surface expression of TNFR2 followed by intracellular staining for TNF." (PMID 23874808, 2013). "During a mild influenza infection, the capacity of the responding CD8 T cells to produce TNF increases from day 6 through day 12, beyond the time of viral clearance." (PMID 23874808, 2013). "We selected three important inflammatory cytokines (TNF-α, IL-6, and IFN-γ) to evaluate the cytokine burst in lethally influenza-infected mice." (PMID 24373231, 2013). "We used a polyfunctional ICS assay detecting the effector molecules IFN-γ, TNF-α, MIP-1β, IL-2 and CD107a, to compare the quality of influenza- and SIV-specific CD8 T cells." (PMID 22403659, 2012). "Pandemic influenza vaccines should preferentially activate both Th1 (IL-2, IFN-γ and TNF-α) and Th2 subsets (IL-4, IL-5, and IL-10) of T helper cells, since both are important for elimination of influenza virus from the host." (PMID 22069479, 2011). "Furthermore, as autocrine TNF enhances B cell proliferation, and TNF is produced in abundance by plasma cells; TNF blockade may inhibit this process, contributing to the reduced development of influenza-specific memory B cells and plasmablasts that we observed." (PMID 22177419, 2011). "Multiparametric flow cytometry assays were performed to determine the relative importance of the subpopulations of influenza-specific CD3+CD4+ and CD3+CD8+ T cells that produce IL-2, IFN-γ, and TNF-α." (PMID 20520820, 2010). "The concentrations of the cytokines IL-1β, IL-6, TNF-α, CXCL1,CXCL2, CCL5, IFN-γ and IL-12p40 were evaluated in lung homogenates ofcontrol and Influenza infected mice." (PMID 21079759, 2010). "In addition, a recent study showed that induction of TNFα responses may be important in the development of more effective B and T cell recall responses against influenza suggesting that a vaccine that enhances T cells with TNFα effector function may influence its ability to confer durable immunity." (PMID 20544035, 2010). "Additionally, airway Tregs upregulated influenza infection, IFN-α/β signaling, and IFN-γ signaling pathways, but downregulated IL-2 production, TGF-β, TNF-α, Toll-like receptor (TLR), TCR, and MAPK signaling pathways in COPD." (PMID 40589761, 2025). "SCoV2/D614G infection induced the mRNA levels of IFN-β, IFN-λs, IL-8, IP-10, ISG15, MDA5, and TNF-α compared with the mock infection, where the induction of interferons (IFN-β, IFN-λ1, and IFN-λ2/3) and MDA5 were greater than that of the influenza H1N1 and H3N2 infections." (PMID 40431161, 2025). "In the case of serotype B influenza, seroprotection was not achieved, with an average increase in titres of 15%, 0% and 22% in the anti-TNFα therapy, MTX therapy and healthy control groups, respectively." (PMID 40281592, 2025). "Decursin significantly reduces viral load in the lungs of influenza-infected models (>1 log), downregulates the ratio of p-PI3K/PI3K and p-Akt/Akt, and regulates the balance of IL-6, IL-17, TNF-α, and IL-10, effectively alleviating morphological abnormalities in lung tissue." (PMID 40860873, 2025). "In the analysis of patients who had never received the influenza vaccine based on the medications they used, those receiving anti-TNF-α and csDMARD treatment had more severe disease (P < .0001, P = .0061)." (PMID 40757797, 2025). "Furthermore, this study provides an effective strategy applicable for designing and engineering nanoscale multivalent drugs targeting other disease proteins, such as S in MERS-CoV, HA in influenza, Env in HIV, F protein in RSV, and TNF-α in cancer." (PMID 38341574, 2024).
influenza (continued). "Inhibition by lefamulin as early as on Day 3 (but not on Day 6) correlates with reduced IL-6 and TNF-α levels and seems to be related to the reduction in influenza progression and pro-inflammatory response." (PMID 38791439, 2024). "While TNF-α is often elevated in inflammatory conditions, studies describe TNF-α as downregulated in SARS-CoV-2-infected hamsters or variably upregulated in both SARS-CoV-2 and influenza infection." (PMID 38400021, 2024). "To determine whether IFN-γ and TNF mediate the observed inflammasome activation, we treated aged-influenza infected mice with neutralizing antibodies against both IFN-γ and TNF starting 21dpi and observed a decrease in caspase-1 activity." (PMID 38077031, 2023). "The induction of type I IFN needs to be tightly controlled, as it was shown in healthy individuals that inhalation of a TLR7 agonist was initially well tolerated after the first dose, but led to an increased TNF-α and IFN I response and influenza-like symptoms, after a second dose." (PMID 36978183, 2023). "Exposure to aerosols generated from VG/PG with and without nicotine caused greater influenza-induced production in the distal airspaces of the pro-inflammatory cytokines IFN-γ, TNFα, IL-1β, IL-6, IL-17A, and MCP-1 at 7 days post inoculation (dpi)." (PMID 36999019, 2023). "Next, we tested the efficacy of neutralizing IL-1β in influenza-infected aged mice and observed dramatic attenuation of lung fibrosis, which phenocopies the results of CD8+ T cell depletion, and neutralization of IFN-γ and TNF." (PMID 38077031, 2023). "Similarly, we found that ONP-302 treatment led to a significant 2-fold reduction in another inflammatory cytokine, TNF-α, in the BALF of aged, influenza-infected mice (P = 0.0130) as compared with controls." (PMID 35737459, 2022). "When fluorescently labeled primary human peripheral blood mononuclear cells (PBMCs) were flowed through the endothelium-lined vascular channel 24 hpi with influenza H3N2, we detected upregulation of ICAM1 and TNF in the endothelial cells by qPCR, indicating endothelial inflammation." (PMID 35396513, 2022). "Cytokines such as IL-4, IL-5, IL-6, IL-8, IL-13, and TNF-α, chemokines such as CCL2 and CCL3, and the MC proteases tryptase and chymase can be detected in the supernatants of influenza infected MC cultures and in the bronchioalveolar lavage fluid (BALF) of both influenza patients and infected mice." (PMID 33680987, 2021). "Likewise, bafilomycin A1, erythromycin, and clarithromycin were studied to impede the making of IL-1β, IL-6, IL-8, TNF-α, and intercellular adhesion molecule (ICAM)-1 in influenza and rhinovirus-modeled infections." (PMID 33937285, 2021). "Heat-killed L. casei DK128 shows similar anti-inflammatory effects against influenza infection by decreasing influenza virus-induced pro-inflammatory cytokines (IL6 and TNF-α), monocytes, and activated NK cells in the lungs of mice, thereby preventing pulmonary inflammation." (PMID 33897683, 2021). "In vitro restimulation with influenza induced increased production of TNF-α by CD8+ T cells in the LAIV but not the TIV or unvaccinated group." (PMID 33497364, 2021). "Intra cellular cytokine staining revealed that the majority of CD8 influenza specific T cells in the BAL secreted IFNγ and TNF (39.9%), followed by IFNγ only producers (35.7%) and 14.5% produced all three cytokines (IFNγ, TNF, and IL-2), while CD4 T cells produced mainly IFNγ (49.3%)." (PMID 33193445, 2020). "TNF-α also increases expression of pro-inflammatory pathway intermediates—IRF1, IRF7, RIG-I, and IKKε–and reduces viral replication in cultured human lung epithelial cells infected with influenza." (PMID 32974217, 2020). "Alternatively, TNF-α blockade has shown therapeutic potential to limit harmful inflammatory responses to influenza without impairing viral control." (PMID 32974217, 2020).
influenza (continued). "Murine models of severe influenza treated with TNF-alpha inhibitors had reduced cytokine production without changes in survival rates." (PMID 32932930, 2020). "Several pathways were inflammation-related, including NF-kappa B signaling pathway, toll-like receptor signaling pathway, TNF signaling pathway, influenza A, NOD-like receptor signaling pathway (data not shown)." (PMID 32523531, 2020). "LPS administration 4 days after influenza infection resulted in a synergistic increase in TNF-α, IL-1β, and IL-6 concentrations in lung tissue, but not in plasma." (PMID 29978355, 2018). "This neutrophil dependence for IL-1β release was not seen with other cytokines, with BALF IL-6 and TNF-α levels comparable between influenza-infected control and neutrophil-depleted mice." (PMID 29079611, 2018). "This is consistent with our observation that the CLEC5A−/− BMMs secreted significantly lower levels of IP-10 but not TNF-α than the CLEC5A+ BMMs after influenza infection." (PMID 27795434, 2017). "This is in agreement with previous findings that after A(H1N1)pdm09 exposure, a primed IFN-γ-IL2+TNF-α+ non-polarized precursor T-cell population (Thpp) has been observed, representing a recently induced memory response to influenza." (PMID 26606759, 2015). "In contrast to our observations in influenza infection, the TNF-α mRNA levels after Ad-OVA infection were not significantly different." (PMID 25251060, 2014). "Two other oil-in-water nanoemulsions, when formulated with smallpox, HIV-1, influenza, or hepatitis B antigens and delivered intranasally, mediated the production of not only robust virus neutralizing antibodies, but also IFN-γ and TNF-α, as well as elevated IgG2a and mucosal IgA levels." (PMID 26344621, 2014). "This is demonstrated by the presence of genes such as TNF and DDX58 in the influenza conserved regulators, which are known to be important regulators during influenza virus infection, and suggests that our prioritization approach has successfully promoted important genes to the top of the rankings." (PMID 23935999, 2013). "In general, response to influenza vaccine was not influenced by therapy or disease activity, but patients using anti-TNF alpha drugs presented lower seroconversion to H1N1 strain." (PMID 23510667, 2013). "We also assessed mMSC efficacy after incubation with IFN-γ and TNF for 24 hours before harvesting for injection; however, this approach failed to improve survival in our murine model of severe influenza (data not shown)." (PMID 23967240, 2013). "The IFNγ−IL-2+TNFα+ influenza-specific cells in the present study did not express CXCR5, and so do not fit a Tfh definition or the more stringent Tcm definition used in one study." (PMID 23526940, 2013). "To determine the possible impact of ST2 on pulmonary inflammation during influenza infection, we measured lung levels of cytokines (IFN-γ, TNF-α, IL-1β, IL-6, IL-10, IL-33, IL-13, IL-5) and chemokines (KC, MIP-2) at 3, 8 and 14 days following influenza inoculation." (PMID 23483993, 2013). "PBMCs from pneumococcal colonised (n = 10) and non-colonised (n = 8) adults stimulated ex vivo with influenza antigen elicited similar frequencies of TNF+, IL-17A+ and IFNγ+ CD4+ memory T-cells." (PMID 23555269, 2013). "TNFα remained below the limit of detection during influenza infection, whereas IL-5 and IL-13 were not induced by influenza infection (data not shown)." (PMID 23483993, 2013). "The objectives of this study were to evaluate the frequency of ARI and ILI in JIA patients and how they affect disease activity, and to assess immunogenicity, safety and efficacy of influenza vaccine in JIA patients treated with potentially immunosuppressive drugs, including anti-TNFα." (PMID 23510667, 2013).
influenza (continued). "Having established that the OT-I T cells could express TNF and TNFR2 during an influenza-OVA infection, we next examined the impact of intrinsic TNF deficiency on the recovery of the OT-I T cells in the mouse from day 6 through 12 of infection." (PMID 23874808, 2013). "Although TNFR1 has been reported at low levels on CD8 T cells and TNFR1 is involved in T cell proliferation in allogeneic models we focused here on TNFR2/TNF interactions, as TNFR2 was the predominant receptor detected on the CD8 T cells in the influenza infected mice." (PMID 23874808, 2013). "The human CD4 T cell memory response to influenza is normally skewed strongly to the Th1 pattern of cytokine expression, including mainly cells secreting IFNγ, TNFα and IL-2 but not IL-4." (PMID 23526940, 2013). "We analyzed in detail the proportion of CD8 T cells producing a number of effector molecules (IFN-γ, TNF-α, CD107a and MIP-1β) at different time-points following SIV challenge in fresh blood samples from one animal with robust influenza and SIV-specific CTL responses." (PMID 22403659, 2012). "In mice, significant levels of TNF and IL-1β were observed following infection with Mtb and Fuj/02 influenza, whereas no cytokines were detected following exposure to PR8 or Schu S4." (PMID 21789257, 2011). "Other than TNF and IL-beta, inflammation-related genes that are well established in influenza infection do not discriminate between these groups." (PMID 21408152, 2011). "Furthermore influenza-specific CD8+DbNP366+ and DbPA224+CD8+ T cells were stimulated in vitro with relevant peptide and cytokine expression (IFN-γ, TNF-α and IL-2) detected using intracellular cytokine staining." (PMID 21304882, 2011). "It is currently not known what role TNFα plays in controlling influenza infection but, like IFNγ, TNFα is known to have direct antiviral effects and is a dominant cytokine produced during influenza virus infections." (PMID 20544035, 2010). "It was shown earlier, that proinflammatory cytokines (IL-1β, IL-6, TNF-α, IFN-α) and microglial reactivity were increased, while neurotrophic (BDNF, NGF) and immunomodulatory (CD200, CX3CL1) factors were decreased in the hippocampus of influenza infected adult mice." (PMID 41567998, 2025). "In addition, IMP321 has been described to enhance the response of Th1 influenza-specific CD4+ cells by increasing the secretion of IFN-γ, the prototypical Th1 effector cytokine, TNF-α, an inflammatory cytokine, and IL-2, which is involved in the development of memory T cells." (PMID 36680187, 2023). "Moreover, both the 500 nm and 3 μm influenza conjugates induced significantly higher numbers of cytokine-producing CD4+ T cells and induced increased production of the pro-inflammatory cytokines IFNγ and TNFα." (PMID 35890185, 2022). "Interestingly, both the exposure of PBMCs to 500 nm and 3 μm influenza conjugates resulted in a significant increase in the frequency of CD4+ T cells producing IFNγ and TNFα and in total amounts of these cytokines compared to exposure of PBMCs to unconjugated particles." (PMID 35890185, 2022). "The finding that influenza infection curtailed the production of IFN-γ in the triple co-culture condition led us to investigate whether these changes impacted the ability of T cells to secrete two of the signature TH1 cytokines, IFN-γ and TNF." (PMID 36618376, 2022). "Meanwhile, when the trivalent influenza vaccine was administered to RA patients, patients treated with only methotrexate had higher antibody titers specific for influenza antigens as compared to patients that were treated with TNF-alpha blockers with or without methotrexate." (PMID 34136315, 2021).
influenza (continued). "In this study, we observed that B.dorei administration decreased production of several cytokines (IL-1β, IL-6, IL-10,TNF-α, MCP-1, and IP-10) in lung and serum induced by influenza infection, which may alleviate excessive inflammatory response and ameliorate immunopathologic damage." (PMID 35154087, 2021). "Furthermore, exogenous administration of recombinant human TRX significantly improved the survival rate and attenuated the histological changes in lungs in a mouse model of influenza pneumonia by diminishing the production of TNF-α and CXCL1 in the lungs observed in influenza-inoculated mice." (PMID 32244938, 2020). "Furthermore, in RAW264.7 cells, SAHA significantly reduced the expression of TNF‐α and IL‐6 in macrophages after LPS stimulation;34 TSA also reduced the IL‐1β level in the serum of a mice model of post‐influenza pneumonia but, interestingly, the acetylation level of histone H3 was not affected." (PMID 32061096, 2020). "Similarly, rfhSP-D has been shown to neutralize and downregulate pro-inflammatory cytokines in vitro including TNF-α, interferon (IFN)-α, IFN-β, interleukin (IL)-6, and regulated on activation normal T-cell expressed and secreted (RANTES), upon influenza infection of a basal epithelial cell line." (PMID 33542724, 2020). "Therefore, FT-induced reduction of TNFα, COX-2, and iNOS may exert protective effects against influenza-induced inflammatory responses." (PMID 32854331, 2020). "(A) Quantification of IFNα and TNFα in supernatants of human pDCs cocultured with DENV-infected (DENV cells) or uninfected BHK-21 cells (Mock), in presence of synthetic TLR7 agonist: Imiquimod; IMQ; 1 μg/mL or influenza infectious supernatant; Flu; 3 × 103 FFU." (PMID 29914621, 2018). "Thus, our model is the first to directly demonstrate that on balance, the strong TNF-α response to influenza–S. pneumoniae coinfection is protective, rather than a driver of immunopathology." (PMID 26265006, 2015). "When formulated with smallpox, HIV-1, influenza, or hepatitis B antigens and delivered intranasally, these adjuvants mediated the production of not only robust virus neutralizing antibodies, but also IFN-γ and TNF-α, as well as elevated IgG2a and mucosal IgA levels." (PMID 26344621, 2014). "This is in line with previous studies which have shown that anti-TNFα therapy does not prevent serologic responses to influenza vaccination, although titres may be somewhat lower." (PMID 24931640, 2014). "We showed previously that CD8+ T-cell-specific TNF-α-deficiency does not impair either virus clearance or immune protection against an otherwise lethal influenza infection, indicating that TNF-α neutralization may not compromise the antiviral response." (PMID 24223177, 2013). "Thus we suggest that while not the major mechanism of T cell contraction following influenza infection, T cell intrinsic TNF fine-tunes the final stages of contraction of the response after viral clearance." (PMID 23874808, 2013). "A possible additional and not mutually exclusive point of impact for TNF blockade is limiting the maintenance of influenza-specific plasma cells, because TNF enhances plasma cell survival in vitro, and has been suggested to be important for plasma cell survival in vivo." (PMID 22177419, 2011). "However, unlike IL-6 and TNF, the fulminant influenza infections observed in untreated mice actually induce 4-fold higher levels of interferon γ than the NTHi lysate treatment." (PMID 19137067, 2009). "Influenza infection induced expression of primary miRNAs rather than enhancing precursor miRNA processing and the changes in expression were far more potent than those triggered by anti-viral molecules such as interferons, interleukin-6 and TNFα in human respiratory cells." (PMID 24116168, 2013).